TBX18 (T-box transcription factor 18)
Description:
Acts as a transcriptional repressor involved in developmental processes of a variety of tissues and organs, including the heart and coronary vessels, the ureter and the vertebral column. Required for embryonic development of the sino atrial node (SAN) head area.
Synonyms: CAKUT2; PUJO
Tractability: No criterion of Open Targets' tractability assessment is met for any kind of drug.
Gene: Protein-coding gene on chromosome 6 (84,687,351 to 84,764,598, reverse strand). Ensembl gene ENSG00000112837.
Subcellular location: Nucleus
Subcellular location (Human Protein Atlas): Nucleoplasm
Gene Ontology:
Molecular function: protein binding; sequence-specific double-stranded DNA binding; DNA-binding transcription factor activity, RNA polymerase II-specific; DNA-binding transcription repressor activity, RNA polymerase II-specific; RNA polymerase II cis-regulatory region sequence-specific DNA binding; DNA-binding transcription factor activity
Biological process: regulation of SA node cell action potential; sinoatrial node cell development; sinoatrial node cell fate commitment; ureter development; cell fate specification; cochlea morphogenesis; morphogenesis of embryonic epithelium; negative regulation of canonical Wnt signaling pathway; negative regulation of transcription by RNA polymerase II; neural plate anterior/posterior regionalization; regulation of transcription by RNA polymerase II; sinoatrial node development; smooth muscle cell differentiation; somitogenesis; positive regulation of DNA-templated transcription; regulation of DNA-templated transcription
Cellular component: nucleoplasm; nucleus; chromatin; RNA polymerase II transcription repressor complex
Genetic constraint (gnomAD): Loss-of-function variants: 19 observed, 49.8 expected, observed/expected ratio (o/e) 0.38, 90% interval 0.26 to 0.56. The upper end of that interval is the gene's LOEUF score, 0.56, which puts it in group 2 of 6, group 1 being the genes least tolerant of losing a copy. Missense variants: 830 observed, 773.96 expected, observed/expected ratio (o/e) 1.07, 90% interval 1.01 to 1.14. Synonymous variants: 341 observed, 314.69 expected, observed/expected ratio (o/e) 1.08, 90% interval 0.99 to 1.18.
Homologues: Orthologues: chimpanzee TBX18 (99% identical), pig TBX18 (96% identical), rabbit TBX18 (96% identical), guinea pig TBX18 (95% identical), mouse Tbx18 (94% identical), rat Tbx18 (93% identical), dog TBX18 (87% identical), macaque TBX18 (86% identical), tropical clawed frog tbx18 (75% identical), zebrafish tbx18 (62% identical), Drosophila melanogaster org-1 (26% identical), Caenorhabditis elegans mls-1 (19% identical). Paralogues in human: TBX15 (56% identical), TBX22 (37% identical), TBX20 (29% identical), MGA (28% identical), TBX3 (27% identical), TBX2 (26% identical), TBX4 (25% identical), TBX1 (24% identical), TBX5 (24% identical), TBX6 (23% identical), TBX10 (23% identical), TBR1 (22% identical), and 4 more.
Diseases named in the same sentence as TBX18 in open-access papers:
TBX18 is named in the same sentence as 41 diseases in open-access papers, as found by Europe PMC text mining. Sharing a sentence is not in itself a finding about the gene and the disease. The quoted sentences say what the papers report.
hydronephrosis (3 papers, 2014 to 2024). Collection of urine in the renal pelvis that results in dilatation of the renal pelvis and calyces. "A recent study has attempted to disrupt Smad4 with Tbx18-Cre transgenic line, and the mutant embryos displayed hydronephrosis at E17.5." (PMID 25127126, 2014). "We found that mice with specific deletion of Smad4 in Tbx18-expressing ureteral mesenchyme exhibited hydroureter and hydronephrosis at embryonic day (E) 16.5, and the mutant mesenchymal cells failed to differentiate into SMCs with increased apoptosis and decreased proliferation." (PMID 25127126, 2014).
Hydroureter (3 papers, 2014 to 2025). The distention of the ureter with urine. "In another study, conditional deletion of Gata2 in the mesenchyme using Tbx18-Cre resulted in hydroureter formation at birth." (PMID 40196482, 2025). "The m6A levels of BMP4, TBX18 and SOX2 mRNAs were lower in the ureter samples from patients with megaureter (M group) than those from patients with VUR (V group)." (PMID 35795641, 2022).
myocardial infarction (3 papers, 2017 to 2025). Gross necrosis of the myocardium, as a result of interruption of the blood supply to the area, as in coronary thrombosis. "While most epicardium goes into dormancy exhibiting limited proliferation ability after birth, some can be reactivated to re-entre into cell-cycle by myocardial infarction (MI) and re-express genes resemble to embryonic epicardium, such as TBX18 and RALDH2." (PMID 39825425, 2025).
atrioventricular block (2 papers, 2025 to 2026). A heart block that is initiated in the atrioventricular node. "In a porcine model of complete atrioventricular block, chemically modified TBX18 mRNA was delivered via intramyocardial injection to reprogram ventricular cardiomyocytes into pacemaker-like cells." (PMID 40843724, 2025). "In a complete AV-block rat model, AAV-mediated Hcn2 expression induced robust ectopic pacemaker activity in the presence of isoproterenol, whereas TBX18 expression neither generated such activity nor augmented Hcn2-mediated pacing." (PMID 42275147, 2026).
congenital heart defect (2 papers, 2017 to 2022). "Variations in NOTCH2, NOTCH3, TTN, TBX4, TBX10, TBX18, and TBXAS1 are associated with congenital heart disease." (PMID 29381953, 2017).
glioblastoma (2 papers, 2020 to 2024). The most malignant astrocytic tumor (WHO grade IV). "Through the further functional enrichment analysis of dysmethylated genes, such as CXCR4, TBX18, SP5, and TMEM22, several potential pathogenic functions are found to participate in the initiation and progression of glioblastoma." (PMID 33329750, 2020).
Obesity (2 papers, 2024 to 2025). Accumulation of substantial excess body fat. "Additionally, TBX18 is related to obesity in humans and mice." (PMID 39408884, 2024).
Arrhythmia (1 paper, 2021). Any cardiac rhythm other than the normal sinus rhythm. "Another experiment in porcine VMs also indicated that TBX18 expression did not increase the risk of arrhythmia, which means that a mixed-current approach is probably a superior means of producing a bio-pacemaker." (PMID 33690622, 2021).
Bradycardia (1 paper, 2024). A slower than normal heart rate (in adults, slower than 60 beats per minute). "A single dose of synthetic TBX18 mRNA to the myocardium transiently increased the heart rates of rats and pigs in severe bradycardia over the course of 2 or 4 weeks, respectively." (PMID 38698155, 2024).
cardiomyopathy (1 paper, 2021). A disease of the heart muscle or myocardium proper. "TBX18 gene delivery resulted in antegrade conduction rescue in a preclinical model of right ventricular pacing-induced cardiomyopathy." (PMID 34409019, 2021).
cleft palate (1 paper, 2023). Cleft palate is a fissure type embryopathy that affects the soft and hard palate to varying degrees. "Thus, Wnt1-Cre and Tbx18-Cre both yielded craniofacial defects (cleft palate, macrostomia) and omphaloceles." (PMID 38079449, 2023).
fibrosis (1 paper, 2023). the formation of excess fibrous connective tissue in an organ or tissue in a reparative or reactive process. "We also observed a similar induction of gene programs associated with ECM remodeling and the wound healing response following the analysis of pericytes acquired from the Tbx18 lineage 7 days after MI, suggesting that pericytes may be a regulator of cardiac fibrosis." (PMID 37183820, 2023).
glioma (1 paper, 2020). A benign or malignant brain and spinal cord tumor that arises from glial cells (astrocytes, oligodendrocytes, ependymal cells). "According to recent publications, an independent study in 2015 confirmed that microRNA miR-205 prevent the invasion of glioma by targeting TBX18, reflecting the potential regulatory role of TBX18 during glioma pathogenesis." (PMID 33329750, 2020).
heart failure (1 paper, 2020). Inability of the heart to pump blood at an adequate rate to meet tissue metabolic requirements. "Of the transcription factors known or predicted to regulate HCN4 (AP1, Isl1, Mef2c, Nkx2.5, NRSF, Tbx3 and Tbx18), two (Nkx2.5 and Tbx3) did not change in the sinus node in heart failure." (PMID 32647133, 2020). "In the heart failure mice, qPCR showed no significant change in Bmp2, Bmp4, Nkx2.5, Shox2 and Tbx3 in the sinus node, but there was a significant downregulation of Tbx18 and Isl1 and upregulation of AP1, Mef2c and NRSF mRNA." (PMID 32647133, 2020). "In summary, we have identified five factors that could be involved in the downregulation of HCN4 in the sinus node in heart failure: Isl1, NRSF, Tbx18, miR-139-3p and miR-370-3p." (PMID 32647133, 2020).
hydrops (1 paper, 2023). "Tbx18-Cre Ift140 deletion caused hydrops and polydactyly with high penetrance, but cardiovascular anatomy was largely unaffected except for some perimembranous VSDs." (PMID 38079449, 2023).
idiopathic pulmonary fibrosis (1 paper, 2023). Idiopathic pulmonary fibrosis (IPF) is a nonneoplastic pulmonary disease that is characterized by the formation of scar tissue within the lungs in the absence of any known cause. "Snitow reported that EZH2 loss reduces the expression of myocardin and TBX18, thereby affecting the autonomic inhibition of smooth muscle differentiation in mesothelium cells, and ultimately contributing to the development of COPD and idiopathic pulmonary fibrosis." (PMID 38114929, 2023).
ischemic stroke (1 paper, 2024). A stroke disorder caused by obstruction of blood flow to the brain, due to thrombotic (local blood clot formation) or embolic (due to a blood clot or other material traveling from another site) event. "We transcriptionally profiled a total of 732 Tbx18-tdT+ cells from the naïve group, 4315 Tbx18-tdT+ cells from the physical injury group (saline injections) and 2219 Tbx18-tdT+ cells from the ischemic stroke group (ET-1/L-NAME injections)." (PMID 39431007, 2024). "Second, we show that NG2+ pericytes have a strong neurogenic potential following ischemic stroke by generating RGPs, while Tbx18+ pericytes exhibit a strong potency to produce endothelial cells following ischemic stroke." (PMID 39431007, 2024). "Recent work also discloses the occurrence of Tbx18-derived fibroblasts following either a cortical stab injury model or a permanent focal ischemic stroke model 14,18." (PMID 39431007, 2024). "Although Tbx18-tdT+ cells can generate a small number of Sox2+ i-NSCs following ischemic stroke at both 1 and 3 dpi, they barely produce DCX+ neuroblasts and Olig1+ OL lineage cells." (PMID 39431007, 2024). "NG2+ pericytes expressed dominant neural reprogramming potential to produce newborn neurons, while Tbx18+ pericytes displayed dominant multipotency to produce endothelial cells, fibroblasts, and microglia following ischemic stroke." (PMID 39431007, 2024). "On the other hand, recent single-cell RNA-sequencing (scRNA-seq) analysis of Tbx18-tdT+ pericytes shows that Tbx18 expressing pericytes can produce fibroblasts, endothelial cells, and microglia following ischemic stroke by photothrombosis." (PMID 39431007, 2024). "After pre-processing, the three Tbx18+ groups including naïve, physical injury, and ischemic stroke, were integrated for downstream analysis." (PMID 39431007, 2024). "Brain pericyte-derived endothelial cells, fibroblasts and microglia following ischemic stroke have all been confirmed with genetic fate mapping using either Tbx18-CreERT2/Rosa26-tdTomato, Glast-CreERT2/Rosa26-tdTomato, or Rgs5-YFP mouse lines 11,14,15." (PMID 39431007, 2024). "As expected, the percentage of Tbx18-tdT+ cells that are adjacent to CD31+ micro-vessels were significantly reduced following both physical injury and ischemic stroke injury." (PMID 39431007, 2024).
prostate disease (1 paper, 2016). "In these morphological characteristics, the abnormal stromal cells in Tbx18 mutant prostates resemble myofibroblasts, which are frequently associated with prostate pathologies." (PMID 27120339, 2016). "Whatever their origins, the appearance of MFBs in the Tbx18 mutant stroma provides a potentially novel link between the developmental activities of this T-box factor and predisposition to adult prostate disease." (PMID 27120339, 2016). "Together, our data indicate an important role for Tbx18 in regulating the reciprocal epithelial-stromal signaling from the earliest stages of prostate development, with implications for human prostate disease." (PMID 27120339, 2016).
renal carcinoma (1 paper, 2024). A carcinoma arising from the epithelium of the renal parenchyma or the renal pelvis.
Stroke (1 paper, 2024). Sudden impairment of blood flow to a part of the brain due to occlusion or rupture of an artery to the brain. "For instance, expression of 2 transcription factors in the Fb-V cluster (foxf2a, tbx18) are associated with pericytes in previous studies, although have poorly described roles, and regulatory changes in FOXF2 are associated with stroke in humans." (PMID 38683849, 2024).
ventricular fibrillation (1 paper, 2024). A disorder characterized by an electrocardiographic finding of a rapid grossly irregular ventricular rhythm with marked variability in QRS cycle length, morphology, and amplitude. "We observed one incidence of unexpected death in a pig treated with TBX18 mRNA, experiencing spontaneous sustained ventricular fibrillation, the cause of which could not be determined." (PMID 38698155, 2024).
ventricular septal defect (1 paper, 2018). The presence of a defect (opening) in the septum that separates the two ventricles of the heart. "However, heterozygous variants within the TBX18 gene promoter were reported in 4 out of 326 individuals with a ventricular septal defect, while no functional variants were found in a control group (n = 327)." (PMID 29904178, 2018).
ventricular tachycardia (1 paper, 2024). A disorder characterized by an electrocardiographic finding of three or more consecutive complexes of ventricular origin with a rate greater than a certain threshold (100 or 120 beats per minute are commonly used). "PES induced non-sustained ventricular tachycardias in four of five GFP-injected rats and in three of six mRNA TBX18-injected rats." (PMID 38698155, 2024).
tumor (5 papers, 2020 to 2025). "Most of these mutations were detected only in the serially transplanted tumors, except for Tbx18, for which the allelic fraction of the mutation is 6.9% in the primary tumor and increases to 50.9% in the serially transplanted tumor." (PMID 34417556, 2022). "As Tbx18 has been shown to have a role in proliferation and tumorigenesis, this mutation is likely to provide a growth advantage for the transplanted tumor." (PMID 34417556, 2022). "In parallel studies, tumor sections were immunostained for Tbx18::H2B-GFP and smooth muscle actin alpha 2 (ACTA2), a marker for most vSMCs." (PMID 36929001, 2023). "However, little is known about the function of CBLN1 and TBX18 in tumorigenesis and the progression of tumor." (PMID 32441304, 2020).
cardiac disease (1 paper, 2018). "TBX18 is thought to be responsible for the development of the myocytes in the ventricular septum and the atrial and ventricular walls of the heart although cardiac disease-related variants in the human TBX18 gene have not been reported." (PMID 29904178, 2018).
TBX18 also shares sentences with these, for which no sentence is quoted: bacterial infection (1 paper); breast carcinoma (1); cardiovascular diseases (1); deafness (1); epilepsies (1); infarction (1); infection (1); injury (1); ischemia (1); omphalocele (1); orofacial cleft (1); prostate (1); renal diseases (1); renal dysplasia (1); sick sinus syndrome (1); urological diseases (1).